MITF (melanocyte inducing transcription factor)
Diseases named in the same sentence as MITF in open-access papers (continued):
Sharing a sentence is not in itself a finding about the gene and the disease.
melanoma (continued). "We characterized microRNA–mRNA networks in melanoma tissue and cell lines consistent with the current understanding of ‘keratin’ and ‘MITF-low’ melanoma transcriptomic subtypes." (PMID 34771465, 2021). "Melanoma cell phenotype switch can also alter MITF expression, which in melanocytes regulates pigmentation." (PMID 35127523, 2021). "Melanoma identity of the micrometastases was confirmed by immunohistochemical staining for the melanocyte marker MITF." (PMID 34417458, 2021). "It is well known that NK cells become progressively exhausted in the context of melanoma progression, and these data would be consistent with expression of MITF in melanoma cells influencing the exhaustion of these innate immune cells." (PMID 33789714, 2021). "MITF also regulates some genes that are important for melanoma survival (e.g., BCL2), proliferation (e.g., CDK2) and metastatic potential (e.g., c-MET)." (PMID 33746605, 2021). "C21orf91 is therefore a critical molecule controlling proliferation of melanoma cells from at least two pathways, one of which is the canonical pigment-cell phenotype switching pathway driven by MITF." (PMID 34145395, 2021). "The Venn diagram outlined that 37.14% of the 105 MMs (n = 39) displayed positivity for all the examined markers: S100, SOX10, SOX11, MITF, and conventional pan-melanoma cocktail." (PMID 33801642, 2021). "Inhibition of FBXO32 expression ensuing MITF silencing was also verified by qPCR in 501Mel, MeWo, and two short-term melanoma cultures." (PMID 33462405, 2021). "In detail, MITF regulates melanocyte physiology and subsequently dictates fundamental gene expression programs in melanoma." (PMID 34440824, 2021). "Through regulation of genes related to invasiveness, migration and metastasis MITF can promote melanoma progression." (PMID 33875769, 2021). "A-485 has also been found to be effective against high MITF-expressing melanoma cell lines and nuclear protein of the testis (NUT) midline carcinoma." (PMID 34642317, 2021). "Low levels of oxygen reduce MITF expression in melanoma in an indirect hypoxia-inducible factor 1 subunit alpha (HIF-1α)-dependent manner, thereby promoting the invasive, metastatic phenotype." (PMID 34071193, 2021). "Our observations suggest that knocking down MITF leads to a major increase in TGFß1 mRNA expression in the melanoma cells, suggesting that the effects are cell-autonomous and driven by MITF." (PMID 33438577, 2021). "Stimulation of α-MSH in B16-F10 melanoma cells increased the expression of MITF and the melanogenesis-related tyrosinase gene family (TRP-1, TRP-2, and tyrosinase) through the activation of CREB and ERK." (PMID 33804361, 2021). "By controlling melanoma recognition by NK-cells MITF thereby controls the melanoma response to the innate immune system." (PMID 33789714, 2021). "To uncover potential tumor-intrinsic mechanisms that regulate TLS formation, we have taken the novel perspective of evaluating TLS induction in melanomas impacted by common driver mutations in BRAF, PTEN, NRAS, KIT, PRDM1, and MITF." (PMID 33746966, 2021).
melanoma (continued). "Less common melanoma susceptibly genes include CDKN2A/ARF, CDK4 (cyclin-dependent kinase 4), TERT, MITF (melanocyte inducing transcription factor), BAP1 (BRCA1 associated protein-1), and POT1 (protection of telomeres 1)." (PMID 34440462, 2021). "HU reduced MITF gene expression in B16 melanoma cells, and miR-7013-3p assisted HU in reducing MITF gene expression levels." (PMID 33746605, 2021). "This set of 33 fitness genes related to melanoma included melanocyte‐specific transcription factors such as MITF and SOX10, established as fitness genes for cells of the melanocytic lineage." (PMID 32767816, 2021). "Deubiquitinase USP13 deficiency prevented the growth of melanoma in vitro and in vivo; however, MITF overexpression prevented USP13’s inhibition, indicating MITF’s involvement in melanoma development, which was mediated by USP13." (PMID 34179099, 2021). "EMT-like phenotype switching is important for metastatic melanoma progression, and it is orchestrated by MITF, AXL, and EMT-inducing transcription factors (EMT-TFs), such as TWIST, ZEB, and SLUG." (PMID 35008286, 2021). "Thereby, the level of MITF alters melanoma phenotype switch as well as matrix composition and interactions." (PMID 35127523, 2021). "The number of focal adhesion points increased upon MITF knockdown, a feature observed in drug-resistant melanomas." (PMID 33438577, 2021). "In contrast, moderate MITF expression induces phenotype switch from invasive to proliferative state, endowing melanoma cells with a stronger growth advantage." (PMID 34924562, 2021). "Here, we demonstrate that MITF regulates global ubiquitination in melanoma cells, at least in part, through FBXO32." (PMID 33462405, 2021). "TRIM63 was already identified as a MITF target and was reported to be involved in melanoma cell migration and invasion." (PMID 33462405, 2021). "Another possible mediators of miRNA dysregulation in the melanoma are melanoma-inducing transcription factors such as MITF whose role in the expression of a number of miRNAs has been verified." (PMID 33968718, 2021). "In contrast, regulation of EGFR and TGFA occurs by an indirect mechanism, which is enabled by the ability of NRF2 to block the activity of the melanocytic lineage factor MITF in melanoma." (PMID 33916908, 2021). "YY1 acts upstream MITF and cMYC pathways and governs multiple metabolic pathways and protein synthesis in neural crest stem cells and melanoma." (PMID 34638331, 2021). "Kim and colleagues recently demonstrated that melanoma growth is driven by direct control of MITF by the evolutionary conserved master transcriptional coactivator EP300." (PMID 34067022, 2021). "Compelling research works demonstrated the pivotal role of MITF in melanocyte and melanoma through its ability to promote essential biological processes such as differentiation, survival, and proliferation, but also to damper motility and invasion." (PMID 33462405, 2021). "Our results reveal how modulation of MITF activity can impact the anti-melanoma immune response with implications for the application of anti-melanoma immunotherapies." (PMID 33789714, 2021). "Dedifferentiated state of melanoma cells characterized by low MITF level has a higher inflammatory responsiveness and pathway activity." (PMID 34924562, 2021). "High MITF expression sensitizes melanoma cells to BRAF and MEK inhibitors whereas the cells are more proliferative." (PMID 35127523, 2021). "These molecules then bind to the receptors present on melanoma cells and activate Notch signaling, leading to the abolition of the MITF-mediated inhibition of miR-222/221 expression and subsequent increase in melanoma invasion." (PMID 33430277, 2021). "MITF is by far the most intensively studied of these factors regarding melanoma formation, progression, and plasticity due to its prominent role in melanocyte development and melanogenesis." (PMID 34071193, 2021).
melanoma (continued). "Instead EP300 targeted therapy have shown potential in preclinical models of MITF overexpressing melanomas." (PMID 33556121, 2021). "Mass spectrometry analysis of the HIF-2α nuclear interactome in melanoma cells revealed that master proteins involved in melanoma development, such as MITF and SOX10, are HIF-2α binding proteins." (PMID 33964953, 2021). "On the other hand, MITF is also a pigmentation and differentiation inducer, which explains the observation that melanoma stem cells and melanoblasts are amelanotic." (PMID 33870460, 2021). "The MITF plays a critical role in melanocyte differentiation, but also melanomagenesis, allowing the transition of melanoma cells between a differentiated-proliferative phenotype and a stem cell-like phenotype." (PMID 33800394, 2021). "In melanoma cells, Xmrk downregulates the tyrosinase gene, which controls melanin synthesis via MAPK inhibition of the transcription factor, microphthalmia-associated transcription factor (MITF), and suppresses melanocyte differentiation." (PMID 34067095, 2021). "To investigate this possibility, we undertook flow cytometry analysis of the B16/F10 melanoma cells used for the tumor formation assays, using antibodies specific for MITF and MLANA." (PMID 33789714, 2021). "Our study results demonstrate that HuR is a promising target for melanoma treatment and offers new combinatorial treatment strategies for overriding MITF-mediated drug resistance." (PMID 33418925, 2021). "The regulation of melanoma cell phenotypic plasticity by MITF is also attributed to the alteration of cell metabolism." (PMID 34924562, 2021). "Initially investigating melanoma cells lines, where its overexpression downregulated MITF, it was found that miR-137 also decreased the expression of the MITF protein and its downstream genes in transgenic mice." (PMID 34198907, 2021). "The most common MITF genetic alteration is amplification, which occurs in 15–20% of melanomas (more common in metastatic melanomas)." (PMID 34203771, 2021). "We also assessed the expression of PXN in a panel of 163 patient-derived melanoma cells exhibiting different levels of MITF." (PMID 33438577, 2021). "It has been reported that the down-regulation of MITF is related to the acquisition of melanoma stem cells, and MITF is involved in the metastatic growth of melanoma after diffusion." (PMID 34712617, 2021). "miR-203 promotes melanogenesis through the CREB1/MITF/Rab27a pathway by targeting Kif5b in melanoma." (PMID 34831071, 2021). "In melanoma, Remodelin was reported to repress microphthalmia-associated transcription factor (MITF) required for melanogenesis and melanoma growth." (PMID 33723305, 2021). "The observation that MITF controls ADAM10 expression highlights the importance of melanoma phenotype on recognition by the immune system." (PMID 33789714, 2021). "The ‘MITF-low’ network hub comprised the same two microRNAs (miR-100-5p and miR-125b-5p) as were identified in our network analysis of TCGA melanoma tumors and accounted for 308/4489 (7%) of the total microRNA–mRNA inverse correlations in this dataset." (PMID 34771465, 2021). "A stiffer ECM with increased collagen levels induces proliferation and differentiation of melanoma cells via Yes1-associated transcriptional regulator (YAP) and PAX3, which interact and thereby promote MITF expression." (PMID 34071193, 2021). "We previously reported that NRF2 is a strong suppressor of MITF activity and differentiation in melanoma and represses transcriptional activity of MITF." (PMID 33916908, 2021). "MITF acts as a transcriptional regulator to mediate the pigmentation, proliferation, apoptosis and migration of B16 melanoma cells." (PMID 33746605, 2021).
melanoma (continued). "In melanoma, ERK activity stimulated by BRAF is associated with MITF ubiquitin-dependent degradation." (PMID 34571969, 2021). "In BRAF inhibitor-treated melanoma cells, MITF was differentially expressed to promote proliferation (high MITF to induce MLANA, PMEL, TYRP genes) or invasion (low MITF to induce high AXL, WNT5A, TEAD, JUN expression)." (PMID 34066022, 2021). "The identification of MITF after treatment indicates metastatic disease and worse outcomes in melanoma patients." (PMID 34441278, 2021). "Panobinostat, another pan-HDAC inhibitor, is being tested for the treatment of MITF-amplified melanoma (NCT01065467)." (PMID 34944799, 2021). "To address these key issues we developed an immunogenic mouse model, and examined the effect of MITF knockout on the anti-melanoma immune response." (PMID 33789714, 2021). "Our results suggest that MITF plays a critical role as a repressor of gene expression and is actively involved in shaping the microenvironment of melanoma cells in a cell-autonomous manner." (PMID 33438577, 2021). "On the other hand, MITF expression in primary melanocytes and melanoma cells is suppressed under hypoxic conditions by the HIF-1α mediated activation of a transcriptional repressor, the differentially expressed in chondrocytes protein-1." (PMID 33964953, 2021). "We conclude that reduced MITF expression leads to activation of expression of genes involved in ECM and focal adhesion in melanoma cells and tumors and that in many cases this is through direct binding of MITF to their regulatory regions." (PMID 33438577, 2021). "mTORC1 promotes cellular proliferation by activating anabolic pathways and by inactivating catabolic pathways such as autophagy, and the MAPK pathway regulates MITF, introduced above as a major regulator of melanoma proliferation and progression." (PMID 34356645, 2021). "In terms of plasticity, IL-1α and β can downregulate the expression of MITF and melanocytic antigens, favoring melanoma dedifferentiation and phenotype switching." (PMID 34604096, 2021). "At the highest state where c-AMP induction leads to peak MITF activity, melanoma cells express differentiation target genes (i.e., Tyrosinase and MART1), giving rise to a pigmented phenotype and undergoing terminal differentiation." (PMID 34356645, 2021). "Our study results showed the HuR-NP suppressed U0126 induced MITF and produced enhanced antitumor activity in the melanoma cell line." (PMID 33418925, 2021). "TNFα induces BRN2 signaling and, in line with often mutually exclusive expression of BRN2 and MITF, it has been identified as an inhibitor of MITF and Melan A in 40 different melanoma cell lines." (PMID 34604096, 2021). "Not only suppression on downstream melanogenic proteins in human melanoma cells but also lightening of skin tone was reported in a clinical study after treatment with a MITF-repressing agent." (PMID 34641584, 2021). "Previous analysis has shown that knocking down MITF leads to increased migration ability of melanoma cells." (PMID 33438577, 2021). "As demonstrated in UMM066, CYSLTR2 expression was found in melanoma cells that also presented with high expression of pigmentation genes (MITF and TYR) and marker genes of MAPK (Mitogen-Activated Protein Kinase) pathway activation (MPAS)." (PMID 33588787, 2021). "Based on their findings, they developed a BRN2-PAX3 rheostat model that explains how MITF expression is controlled in BRAFV600E mutant melanoma." (PMID 34071193, 2021). "The survival associated mitochondrial melanoma specific oncogenic non-coding RNA (SAMMSON), which is located 30 kb downstream of the MITF gene, regulates the survival of melanoma and is co-amplified with MITF in approximately 10% of human melanomas." (PMID 33435206, 2021).
melanoma (continued). "It was demonstrated that following the co-culture of melanoma cells with aged fibroblasts, the expression of MITF and a redox effector, APE1 (apurinic/apurymidinic endonuclease 1), was decreased in a β-catenin-dependent way." (PMID 33430277, 2021). "As a reaction to stimuli from the microenvironment, melanoma cells can dynamically switch between invasive (MITF-low) and proliferative (MITF-high) phenotypes to promote cell plasticity, tumor heterogeneity and resistance to therapy." (PMID 34573422, 2021). "The same findings were obtained using single cell RNA-seq data of MITF-depleted zebrafish melanomas as well as bulk-RNA-seq data of MITFlow melanoma tumors." (PMID 33438577, 2021). "MITF is also involved in the progression of melanomas and other carcinomas, including the liver, pancreas and lung." (PMID 34208068, 2021). "MITF is considered a driving factor of melanoma progression, but its role in inhibiting invasion and metastasis has also been confirmed." (PMID 34722301, 2021). "About 20% of metastatic melanomas harbor MITF gene amplifications, and MITF expression is detected in the majority of primary melanomas (except for desmoplastic melanoma)." (PMID 34071193, 2021). "Accordingly, we suggest that the Hippo pathway is a strong regulator of melanogenesis, and through a molecular cascade involving MITF and oxidative stress response, controls melanoma growth." (PMID 33803640, 2021). "Within the metastatic melanoma samples, there was a clear difference in the expression of lipid metabolism-related genes based on MITF/AXL status." (PMID 37849907, 2021). "H2O2-induced ATP synthase β induces melanogenesis by activating PAH and cAMP/CREB/MITF signaling in melanoma cells." (PMID 34107850, 2021). "This suggests that the induced expression of ECM genes and low expression of MITF is one of the markers of MRD in melanoma." (PMID 33438577, 2021). "Our study showed that inhibiting HuR reduced HuR-regulated oncoproteins, including MITF, inhibited cell proliferation and cell cycle, diminished melanoma cell’s migration and invasion, and culminated in apoptotic cell death." (PMID 33418925, 2021). "Another 14/40 melanoma cell lines (13/31 cutaneous and 1/9 uveal) displayed the neural crest-like dedifferentiated subtype with low MITF and Melan A, and elevated, albeit variable levels, of AXL and/or NGFR." (PMID 34073253, 2021). "More specific melanoma markers such as Melan-A, HMB-45, SRY-related HMG-box 10 (SOX-10), microphthalmia-associated transcription factor (MiTF) and tyrosinase, should be used together with S100 protein for accurate differential diagnosis." (PMID 34514560, 2021). "MITF plays a critical role in melanocyte development and melanoma carcinogenesis by controlling the expression of several melanoma-associated genes that regulate proliferation and invasion, including MET5 and CDKN2A/p16INK4A5." (PMID 34503213, 2021). "MITF knockdown in B16.F10 melanoma cells results in decreased expression of (TLS-promoting) CCL21 and CXCL10 chemokine levels, in association with reduced immune infiltration/inflammation in the TME and enhanced tumor progression." (PMID 33746966, 2021). "Significantly, siRNA-mediated depletion of MITF blocked the radiation-induced increase in extracellular MICB, consistent with MITF knockdown preventing the shedding of NKG2D ligands in melanoma." (PMID 33789714, 2021).